TNFRSF9 (TNF receptor superfamily member 9)
Diseases named in the same sentence as TNFRSF9 in open-access papers (continued):
Sharing a sentence is not in itself a finding about the gene and the disease.
rheumatoid arthritis (9 papers, 2010 to 2025). A chronic, systemic autoimmune disorder characterized by inflammation in the synovial membranes and articular surfaces. "TNFα, IL-1β, and hypoxia also up-regulate the expression of cytokines, including IL-6, CXCL8 (namely, IL-8), CCL2, CXCL11, CXCL12, and VEGF, as well as the expression of cytokine receptors such as TNFRSF9 in synovial fibroblasts derived from rheumatoid arthritis (RA) patients." (PMID 35967331, 2022).
glioblastoma (8 papers, 2018 to 2024). The most malignant astrocytic tumor (WHO grade IV). "There, genes with a higher expression in glioblastoma compared to astrocytoma were VEGFA, 4EBP1, CCL2, PLAU (uPA), CXCL8 (IL8), CXCL10 (IP10), CASP8, HGF, LIF, CD40, CDCp1, TNFRSF11B (OPG), CD274 (PD-L1), IL6, CXCL1, CCL20 (MIP3α), CCL8 (MCP2), CD244, MMP1, TNFRSF9, CXCL6, MMP10, FGF5)." (PMID 35301393, 2022).
diabetes (7 papers, 2018 to 2025). "Nine biomarkers were positively associated with depressive symptoms in the total sample (CCL11/eotaxin, CCL25, CDCP1, FGF-21, IL-8, IL-10RB, IL-18, MMP-10, TNFRSF9; all p < 0.05) without interaction by diabetes type." (PMID 39799156, 2025). "The lack of diabetes inhibition conferred by the B10 Tnfrsf9 allele in our F1 mice could be that the functional difference conferred by one copy of B10 and NOD Tnfrsf9 is not sufficient to impact T1D development." (PMID 30867509, 2019). "This study demonstrates positive associations of CDCP-1, FGF-21, IL-8, IL-18, eotaxin/CCL11, MMP-10, TNFRSF9, CCL25 and IL-10RB with depressive symptoms in people with diabetes without interaction with diabetes type." (PMID 39799156, 2025).
Sepsis (7 papers, 2018 to 2025). Sepsis is defined as life-threatening organ dysfunction caused by a dysregulated host response to infection. "We re-examined the response to ICI treatment in sepsis using PANscore and found that PD-1 was more expressed in the LowPANscore subgroup, while PD-L1, LAG3, TIGIT, TNFRSF9, CD40, IDO1 were expressed in the HighPANscore subgroup (P<0.05)." (PMID 38239341, 2023). "Gene ontology of these 23 common DEGs showed that apoptotic process (TRAF1, TNFRSF9, ADORA2A, ZBTB16), negative regulation of transcription (SAP30, TSC22D3, ETS2, ZBTB16), and inflammatory response (TNFRSF9, CCL3, ADORA2A) are the main biological processes affected by sepsis treatment." (PMID 30086151, 2018).
diffuse large B-cell lymphoma (6 papers, 2013 to 2025). "The analysis using the TCGA dataset showed that TNFRSF9 was altered in approximately 5% of cases of Cholangiocarcinoma, adrenocortical carcinoma (ACC) and lymphoid neoplasm diffuse large B-cell lymphoma (DLBC), with deep deletion being the dominant alteration." (PMID 34869372, 2021).
malaria (6 papers, 2016 to 2025). Malaria is a serious and sometimes fatal disease caused by a parasite that commonly infects a certain type of mosquito which feeds on humans. "Evidence of malaria induced immunosuppression within our data was also observed in NK and γδ T cell subsets, where multiple co-inhibitory receptors were upregulated during infection (including TNFRSF4, TNFRSF9, TNFRSH18, HAVCR2, LAG3, and PDCD1)." (PMID 37968278, 2023).
osteosarcoma (6 papers, 2017 to 2025). A usually aggressive malignant bone-forming mesenchymal neoplasm, predominantly affecting adolescents and young adults. "The identified immune-related predictive signature, including CD70, TNFRSF9, EGFR, PDGFD and S100A6, will facilitate the development of personalized therapy for osteosarcoma and provide new insights into the role of the tumor immune microenvironment in regulating patients’ responses to chemotherapy." (PMID 34016089, 2021).
prostate carcinoma (6 papers, 2012 to 2025). A carcinoma that arises from epithelial cells of the prostate gland. "AA patients with high levels of both TNFRSF9 and PTN in their sera had the highest risk of dying from prostate cancer." (PMID 35365620, 2022). "The two analytes PTN and TNFRSF9 remained the most predictive features besides the NCCN risk score, and the three features combined predicted prostate cancer-specific mortality with 90% accuracy." (PMID 35365620, 2022). "In addition, AA prostate cancer patients with high levels (>median) of both TNFRSF9 and PTN in their blood at diagnosis had the worst prostate cancer-specific survival independent of disease status [(Adjusted HR = 3.09 (1.36, 7.03)]." (PMID 35365620, 2022). "PTN or pleiotrophin, the second protein marker found to be associated with lethal prostate cancer in AA men, may not have the same immune function that soluble TNFRSF9 exhibits." (PMID 35365620, 2022). "By 10 years, 33% of cases with high levels of both TNFRSF9 and PTN died of prostate cancer compared to only 5% of cases with low levels of one or both of these proteins, highlighting the utility of these blood markers for risk stratification of AA prostate cancer patients." (PMID 35365620, 2022). "A subset of bone marrow samples that displayed a high frequency of CTC-IGC from the prostate cancer patient cohort were stained with HOMER1, TNFRSF9, and LRP1." (PMID 39483900, 2024). "In publicly available data for previously treated patients, high expression of TNFRSF9 and LRP1 significantly correlated with a shorter progression free survival in patients with prostate cancer; HOMER1 was not statistically significant (p-value = 0.183)." (PMID 39483900, 2024).
sarcoma (6 papers, 2016 to 2025). A usually aggressive malignant neoplasm of the soft tissue or bone. "Using both our retrospective cohort of clinical samples, and data from The Cancer Genome Atlas (TCGA), we identify TNFRSF4/OX40 and TNFRSF9/4-1BB as two immune markers of potential relevance to sarcoma." (PMID 35558159, 2022). "OX40/TNFRSF4 and 4–1BB/TNFRSF9 were highly expressed in sarcoma subtypes versus other cancers." (PMID 35558159, 2022).
uveal melanoma (6 papers, 2020 to 2025). A melanoma derived from melanocytes of the uveal tract. "In GSE155452 uveal melanoma cell line (mel202), after romidepsin intervention, the expression of CD274 was significantly increased, and the expression of TNFRSF9 and TNFRSF14 was significantly different." (PMID 34635662, 2021).
colitis (5 papers, 2013 to 2023). Inflammation of the colon. "For example, there was significant induction of Traf1, Tnfrsf9, Hif1a, Slc2a1 and Pim1 in TREG clusters in CPI colitis in comparison with TREG clusters in control mice." (PMID 37872166, 2023).
Stroke (5 papers, 2018 to 2025). Sudden impairment of blood flow to a part of the brain due to occlusion or rupture of an artery to the brain. "Genes related to inflammation such as Ccl5, Cxcl5, Il1a, Tnfsf10, Nfkb1, Tnfrsf1b, Ccr7, Tnfrsf9, Ccl7, Il1b, Il6, and Ccl24 were also downregulated upon MMP-3 KO in male stroke brains." (PMID 39000490, 2024). "TNFβ (also known as lymphotoxin alpha) and TNFRSF9 (also known as CD137), which activate downstream inflammatory pathways, increasing inflammation and CCL19, a protein involved in arteriole growth following ischemia that is correlated with worse outcome following stroke." (PMID 40703679, 2025).
type 1 diabetes (5 papers, 2005 to 2025). "To evaluate the performance of CCI and other competing methods in real dataset, we download a Type-I diabetes mouse dataset that investigates the effect of CD137 (Tnfrsf9) deficiency on regulatory T and CD8 T cells from Gene Expression Omnibus (GEO), accession number GSE269611." (PMID 39851305, 2025). "Tnfrsf9 (encoding CD137) is a candidate gene for the Idd9.3 type 1 diabetes (T1D) susceptibility locus in the nonobese diabetic (NOD) mouse model." (PMID 30867509, 2019).
breast tumor (4 papers, 2017 to 2024). "Furthermore, since the ex vivo expansion of TILs from TNBC sample was recently reported to be enhanced in the presence of 4–1BB agonistic antibody (against CD137, a TNF receptor superfamily member 9), it is possible that this approach could enhance TIL expansion from other breast tumor types." (PMID 29371915, 2017).
ovarian tumors (4 papers, 2013 to 2023). "Increased expression of TNFRSF9 was observed in platinum resistant ovarian tumors, which implies that this gene may promote tumor progression." (PMID 35646692, 2022).
bladder cancer (3 papers, 2021 to 2023). "Though the signature was only significantly associated with ICI-related biomarkers like TNFRSF9, instead of CTLA4, LAG3, HAVCR2 and PDCD1, thus proving that the efficacy of immunotherapy still presents an underprivileged position within the treatment of bladder cancer." (PMID 34322391, 2021).
endometriosis (3 papers, 2022 to 2025). The growth of functional endometrial tissue in anatomic sites outside the uterine body. "The inflammatory proteins Oncostatin-M (OSM), Monocyte Chemoattractant protein 1 (MCP-1) and TNF Receptor Superfamily Member 9 (TNFRSF9) have been shown to be associated with different symptoms of endometriosis." (PMID 35659226, 2022). "In addition, we explored the immune checkpoints (PDCD1, PDCD1LG2, CTLA4, TNFRSF9, and TNFRSF4) expression levels between the endometrium and endometriosis." (PMID 40165344, 2025).
Hodgkins lymphoma (3 papers, 2025 to 2026). A heterogeneous group of malignant lymphoid neoplasms of B-cell origin characterized histologically by the presence of Hodgkin and Reed-Sternberg (HRS) cells in the vast majority of cases. "However, the TNFRSF9 variant, an NFKB pathway member, was found in case #13, who belonged to family with Hodgkin’s lymphoma." (PMID 40995433, 2025).
Lewis lung carcinoma (3 papers, 2022 to 2023). "TNFRSF9 is an important regulator of mast cell function in several pathologies, including Lewis lung carcinoma in mouse models, and TNF production and signaling in mast cells has been recognized as an important aspect of their function for decades." (PMID 37113661, 2023).
liver fibrosis (3 papers, 2019 to 2024). "TNFRSF9 regulates T‐cell depletion and apoptosis through activation of the 4‐1BB/TRAF1 pathway, which may be implicated in the pathogenesis of liver fibrosis as well as NAFLD." (PMID 39720899, 2024).
multiple sclerosis (3 papers, 2020 to 2024). A progressive autoimmune disorder affecting the central nervous system resulting in demyelination. "In multiple sclerosis, TNFRSF9 appears to be involved in cell death via the activation of microglia." (PMID 37834363, 2023).
retinoblastoma (3 papers, 2019 to 2025). A malignant tumor that originates in the nuclear layer of the retina. "FASLG, TNF, TNFRSF9, and TNFRSF1A, genes involved in FAS and TNF pathways, were expressed at significantly higher levels in Y79 retinoblastoma cells treated with magnetic hyperthermia compared to untreated cells." (PMID 31602343, 2019).
thyroid cancer (3 papers, 2025). "Our MR study indicates that targeting TNFRSF9, combined with current immunotherapies, holds significant potential for the treatment of thyroid cancer." (PMID 40072746, 2025). "In our MR analysis, we discovered that genetically predicted circulating levels of TNFRSF9 act as protective factors against thyroid cancer." (PMID 40072746, 2025). "Additionally, there was a notable association between levels of FGF19, IL2RB, TNFRSF9, S100-A12, FLT3LG, and CCL19 and a decreased risk of thyroid cancer." (PMID 40072746, 2025).
AIDS (2 papers, 2015 to 2022). A syndrome resulting from the acquired deficiency of cellular immunity caused by the human immunodeficiency virus (HIV). "Collectively, these findings support previous reports that increased inflammation may follow or induce non-AIDS comorbidities, and further pinpoint PD-L1, VEGFA, LAP TGFβ-1, and TNFRSF9 as possible targets to decrease the risk for malignancies in well-treated PLHIV." (PMID 36157576, 2022).
allergic asthma (2 papers, 2014 to 2023). A asthma with a basis in a pathological type I hypersensitivity reaction. "An antibody against CD137, which is a tumor necrosis factor receptor superfamily member encoded by TNFRSF9, has been reported to alleviate allergic asthma in a mouse model." (PMID 24994897, 2014).
endothelial dysfunction (2 papers, 2023 to 2025). In vascular diseases, endothelial dysfunction is a systemic pathological state of the endothelium (the inner lining of blood vessels) and can be broadly defined as an imbalance between vasodilating and vasoconstricting substances produced by (or acting on) the endothelium. "The top hub genes identified were TNFRSF9, LZIC, TNFRSF8, SLC45A1, GPR157, and SLC25A33, which are induced by P. gingivalis and F. nucleatum and are responsible for endothelial dysfunction in brain cells." (PMID 40104076, 2025). "The top hub genes were TNFRSF9, LZIC, TNFRSF8, SLC45A1, GPR157, and SLC25A33, induced by P. gingivalis and F. nucleatum responsible for endothelial dysfunction in brain cells." (PMID 40104076, 2025). "Similarly, our study revealed genes like TNFRSF9, LZIC, TNFRSF8, SLC45A1, GPR157, and SLC25A33 that contribute to endothelial dysfunction in brain cells due to P. gingivalis and F. nucleatum." (PMID 40104076, 2025).
Epstein-Barr virus infection (2 papers, 2014 to 2024). An infection that is caused by Epstein-Barr virus. "Concurrent deficiencies in PIK3CD and TNFRSF9 result in chronic active Epstein-Barr virus infections in T cells." (PMID 39845086, 2024).
immunodeficiencies (2 papers, 2022 to 2025). "In summary, we identified a novel TNFRSF9 variant associated with immunodeficiency and lymphoproliferation, supported by functional evidence demonstrating its impact on gene expression, AKT and NF-κB signaling pathways, and immune cell function." (PMID 40843003, 2025). "Our findings expand the mutation spectrum of the TNFRSF9 gene and provide new insights into the molecular mechanisms underlying this rare immunodeficiency disorder." (PMID 40843003, 2025).
liver cirrhosis (2 papers, 2023 to 2024). "We found significantly higher expression of markers of T-cell senescence (e.g., PTPRC, TIGIT, and TNF) and exhaustion (e.g., PDCD1, CTLA4, LAG3, and TNFRSF9) in hepatic CD4+ and CD8 + T cells in participants with NASH or liver cirrhosis than in controls." (PMID 37735474, 2023). "Genes related to senescence (e.g., PTPRC, TIGIT, and TNF) and exhaustion (e.g., PDCD1, CTLA4, LAG3, and TNFRSF9) were highly enriched in CD4+ and CD8 + T cells from the participants with liver cirrhosis." (PMID 37735474, 2023).
myocardial infarction (2 papers, 2024 to 2025). Gross necrosis of the myocardium, as a result of interruption of the blood supply to the area, as in coronary thrombosis. "Five proteins deregulated in homozygous LAV-BPIFB4 carriers (e.g. CXCL11, CSF-1, SLAMF7, IL-10RB and TNFRSF9) emerged from a recent proteome-based CV risk model as the top factors predicting myocardial infarction event." (PMID 38468336, 2024). "Studies have shown that inhibition of the TNFRSF9 signaling pathway helps attenuate pathological cardiac remodeling and has a positive effect on improving cardiac function after myocardial infarction." (PMID 40599317, 2025).
myocarditis (2 papers, 2024). Myocarditis is a condition that is characterized by inflammation of the heart muscle (myocardium). "Cardiovascular disorders and myocarditis in MIS-C are related to the reduction in serum TNF-related subfamily member 9 (TNFRSF9) and apoptosis-inducing ligand (TRAIL)." (PMID 39767774, 2024).
ZIKV infection (2 papers, 2025). "Thus, we show that ZIKV infection of brain tumour cells leads to the upregulated expression and secretion of key members of both TNF alpha and TNFSF9/TNFRSF9 signalling pathways." (PMID 40240536, 2025).
acute pancreatitis (1 paper, 2024). An acute inflammatory process that leads to necrosis of the pancreatic parenchyma. "Inflammatory proteins CCL13 and TNFRSF9 also play a promoting role in the development of acute pancreatitis." (PMID 38881734, 2024). "Among these, genetically predicted IL-15RA, monocyte chemoattractant protein-4 (CCL13), and tumor necrosis factor receptor superfamily member 9 (TNFRSF9) showed a significant positive correlation with the occurrence of acute pancreatitis." (PMID 38881734, 2024). "Additionally, we have discovered three inflammatory proteins that are also associated with the occurrence of acute pancreatitis, namely interleukin-15 receptor subunit alpha (IL-15RA), monocyte chemoattractant protein-4 (CCL13), and tumor necrosis factor receptor superfamily member 9 (TNFRSF9)." (PMID 38881734, 2024).
Alzheimer disease (1 paper, 2025). A progressive, neurodegenerative disease characterized by loss of function and death of nerve cells in several areas of the brain leading to loss of cognitive function such as memory and language. "In Alzheimer's disease, the hub genes TNFRSF9, LZIC, CD30, SLC45A1, GPR157, and SLC25A33 are implicated in immune regulation, cellular transport, neuronal signaling, and mitochondrial function." (PMID 40104076, 2025).
Burkitt lymphoma (1 paper, 2025). A rare form of malignant mature B-cell non-Hodgkin lymphoma. "In conclusion, this study identified a novel homozygous TNFRSF9 variant (p.C120S) in a patient with EBV viremia, recurrent respiratory infections, and Burkitt lymphoma." (PMID 40843003, 2025). "Here, we present a case from a Chinese family featuring Burkitt lymphoma, recurrent respiratory infections, conjunctivitis, and EBV viremia, harboring a homozygous TNFRSF9 variant (c.359G>C, p.C120S)." (PMID 40843003, 2025).
endometrial cancer (1 paper, 2022). Primary or metastatic malignant neoplasm involving the endometrium (mucous membrane that lines the endometrial cavity). "Indeed, cell surface CD39 was the strongest independent predictor of TNFRSF9 expression in TILs from human MSI-H endometrial cancer tumors." (PMID 35454831, 2022).
endometrial tumors (1 paper, 2022). "Here, we report that CD103− CD39+ CD8+ T cells from mismatch repair-deficient endometrial tumors are activated and characterized predominantly by expression of TNFRSF9." (PMID 35454831, 2022).
enteropathy (1 paper, 2014). "For cases on a GFD with remaining enteropathy, results for TNFRSF9 mRNA were in accordance with histopathology for one out of two cases." (PMID 25298177, 2014).
glaucoma (1 paper, 2024). Increased pressure in the eyeball due to obstruction of the outflow of aqueous humor. "Interestingly, we found two members of the complement system central to the network describing GSE4316, CD28 and the TNF receptor superfamily member 9, TNFRSF9, but no entries about the involvement of these genes in glaucoma were found." (PMID 39458974, 2024).
gram-positive bacterial infections (1 paper, 2021). Infections caused by bacteria that retain the crystal violet stain (positive) when treated by the gram-staining method. "CD137, which is encoded by Tnfrsf9, belongs to the tumor necrosis receptor superfamily and has been shown to regulate neutrophils in Gram-positive bacterial infection." (PMID 34068963, 2021).
Hepatic steatosis (1 paper, 2024). Steatosis is a term used to denote lipid accumulation within hepatocytes. "The adverse effects of eotaxin, OPG and TNFRSF9 on NAFLD development underscore the potential role of these inflammatory markers in the pathophysiology of hepatic steatosis." (PMID 39720899, 2024).
injury (1 paper, 2025). Damage inflicted on the body as the direct or indirect result of an external force, with or without disruption of structural continuity. "Conversely, activation of the TNFRSF9 signaling pathway may lead to necrosis of cardiomyocytes, thereby exacerbating myocardial ischemia-reperfusion injury." (PMID 40599317, 2025).